TLR4 (toll like receptor 4)
Diseases named in the same sentence as TLR4 in open-access papers (continued):
Sharing a sentence is not in itself a finding about the gene and the disease.
ascariasis (1 paper, 2021). An infection that is caused by the roundworm Ascaris lumbricoides, many cases of which remain asymptomatic. "This study showed that one of the resistance mechanisms against ascariasis is dependent on TLR2 and TLR4 signaling and the presence of eosinophils, which results in SIgA production." (PMID 34784389, 2021).
axonal neuropathy (1 paper, 2020). Any nerve disorder affecting the axon of a nerve. "In addition to its emerging role in nerve degeneration and axonal neuropathy, MAPK8IP3 may be an important player in the progression of human DPN through its close interaction with Toll-like receptor 4 (TLR4) and JNKs." (PMID 32787975, 2020).
Barth syndrome (1 paper, 2019). Barth syndrome (BTHS) is an inborn error of phospholipid metabolism characterized by dilated cardiomyopathy (DCM), skeletal myopathy, neutropenia, growth delay and organic aciduria. "This has important implications on the synthesis of new modulators of TLR4 to be used as vaccine adjuvants or therapeutics and for understanding the immune response to bacteria as well as the pathology of Barth syndrome both of which involve saturated cardiolipins." (PMID 31062071, 2019).
Bartonella infection (1 paper, 2025). "We identified a polymorphic site in the TLR4 gene that was significantly associated with susceptibility to Bartonella infection." (PMID 40678527, 2025). "Notably, four key sites influencing Bartonella infection susceptibility were identified, with two on TLR1 and one each on TLR4 and TLR10." (PMID 40678527, 2025). "In this study, we analyzed the polymorphisms in six cell surface TLR genes (TLR1, TLR2, TLR4, TLR5, TLR6, and TLR10) in striped hamsters, aiming to determine their association with Bartonella infections and ectoparasite parasitism, including fleas and gamasid mites." (PMID 40678527, 2025). "The genotypes at positions 1331 of TLR1, 36 of TLR4, and 2187 of TLR6 significantly affected Bartonella infection, with MDGs of 3.08, 2.33, and 3.22, respectively." (PMID 40678527, 2025).
benign ovarian tumors (1 paper, 2022). "The normal ovary tissues, benign ovarian tumors, and borderline ovarian tumors were studied to reveal that TLR4, NF-κBp65, and HIF-1α were expressed at a low level, while as cancer progressed, the proportion of the TLR4+ve, NF-κBp65+ve, and HIF-1α+ve EOC cells were significantly increased." (PMID 35464826, 2022).
bone marrow failure (1 paper, 2021). "Here, we demonstrate that lymph node (LN) cells from B6-based donor mice carrying IL-6, TLR2, or TLR4 gene deletions were fully functional in inducing severe pancytopenia and bone marrow failure (BMF) when infused into MHC-mismatched CByB6F1 recipients." (PMID 33711076, 2021).
bovine tuberculosis (1 paper, 2016). "The present study was aimed at exploring the association of seven single nucleotide polymorphisms (SNPs) in TLR2 and TLR4 genes with susceptibility/resistance against bovine tuberculosis (bTB) infection in cattle." (PMID 27284220, 2016).
Brain atrophy (1 paper, 2015). Partial or complete wasting (loss) of brain tissue that was once present. "Future work will be needed to determine the role of metHgb-induced TLR4 activation in vivo in SAH-induced cognitive dysfunction and brain atrophy." (PMID 25751721, 2015).
breast adenocarcinoma (1 paper, 2021). "Indeed, TLR4 induces the expression of T-LAK cell-Originated Protein Kinase (TOPK) that has been proposed to regulate MMP-9 gelatinase expression and activity, thus acting as key mediator of ET-induced migration and invasion of human breast adenocarcinoma cell lines." (PMID 34868543, 2021).
carotid artery thrombosis (1 paper, 2020). Blood clot formation in any part of the carotid arteries. "We have shown FN-EDA activates platelet Toll-like receptor 4 (TLR4) and thus accelerated ferric chloride induces carotid artery thrombosis in mice." (PMID 32499562, 2020).
cerebral palsy (1 paper, 2021). A group of disorders affecting the development of movement and posture, often accompanied by disturbances of sensation, perception, cognition, and behavior. "In a randomized control study, systemic immune reactions such as increased plasma pentraxin‐3, IL8 and TLR4 were observed in cerebral palsy patients treated with umbilical cord blood cells." (PMID 34390186, 2021).
cerebral thrombosis (1 paper, 2022). "HMGB1 induces NETosis via TLR4 and exacerbates damage after cerebral ischaemia and cerebral thrombosis, and TLR4 is also an important signal for activating NETosis." (PMID 35028005, 2022).
Chagas cardiomyopathy (1 paper, 2018). A disease of the cardiac muscle developed subsequent to the initial protozoan infection by trypanosoma cruzi. "Furthermore, TLR-2 and TLR-4 expression are associated with the production of pro-inflammatory cytokines in Chagas’ cardiomyopathy, while in asymptomatic patients these receptors as predominantly associated with IL-10 and TGF-β production." (PMID 29599775, 2018).
Chlamydia pneumonia (1 paper, 2011). "Toll-like receptor 4 has been shown to mediate human β-defensin 2 inductions in response to Chlamydia pneumonia in monocytes." (PMID 21559496, 2011).
Cholestatic liver disease (1 paper, 2016). "In addition, the absence of TLR4 has protective effects against pre-cancerogenous events in cholestatic liver injury, pointing to new avenues for the prevention and therapy of cancer in ABCB4 deficiency and related cholestatic liver diseases." (PMID 27391331, 2016).
chronic bronchitis (1 paper, 2014). A type of chronic obstructive pulmonary disease characterized by chronic inflammation in the bronchial tree that results in edema, mucus production, obstruction, and reduced airflow to and from the lung alveoli. "LPS, a ligand for TLR4, is present in cigarette smoke and may contribute to the pathogenesis of chronic bronchitis." (PMID 24819048, 2014).
chronic idiopathic urticaria (1 paper, 2023). Chronic form of idiopathic urticaria. "Interestingly, a decreased TLR-4 expression on CD14+ cells from chronic idiopathic urticaria patients was observed in ex vivo conditions." (PMID 38045687, 2023).
coccidioidomycosis (1 paper, 2023). A fungal infection caused by Coccidioides immitis. "We hypothesized that cytokine concentrations, serum CRP concentration, and leukocyte TLR2 and TLR4 expression would be different between dogs with coccidioidomycosis and healthy controls." (PMID 36836327, 2023). "Ampel demonstrated that PBMCs from humans with coccidioidomycosis produced lower concentrations of TNF-α when TLR2 and TLR4 were blocked with antibody during stimulation with the coccidioidal extract, T27K, a complex glycoprotein antigen mixture." (PMID 36836327, 2023). "Therefore, TLR4 may be important for controlling the dissemination of coccidioidomycosis." (PMID 36836327, 2023). "Data from six dogs with coccidioidomycosis (pulmonary, n = 4; disseminated, n = 2) were excluded from the analysis of TLR2 and TLR4 expression because of technical difficulties." (PMID 36836327, 2023). "antigen-stimulated leukocyte cytokine production to assess the inflammatory profile, TLR2 and TLR4 expression, and serum CRP concentrations between dogs with newly diagnosed coccidioidomycosis and seronegative healthy controls." (PMID 36836327, 2023).
coccidiosis (1 paper, 2022). A parasitic infection caused by Coccidia. "Among genes that have been reported to be expressed in association with innate immunity responses in chickens infected by coccidiosis are TLR-4, TLR-15, MyD88, and nuclear factor kappa B (NF-κB)." (PMID 36230268, 2022).
colorectal polyp (1 paper, 2020). "A significant association between TLR2 and TLR4 expression levels and location of colorectal polyps was observed." (PMID 33255933, 2020). "The noteworthy point was that the RQs of TLR2, TLR3, TLR4, and TLR5 were significantly different among histologically different colorectal polyp types compared to samples from normal participants (p-value < 0.001)." (PMID 33255933, 2020). "The aim of our study was to evaluate the expression levels of TLR2, TLR3, TLR4, and TLR5 in intestinal biopsy specimens of patients with different histological colorectal polyp types including HP, SSA, tubular adenoma (TA), and villous/tubulovillous (VP/TVP) cases compared to normal controls." (PMID 33255933, 2020).
common variable immunodeficiency (1 paper, 2023). "In this study, we aim to unravel the intricate involvement of TLR2, TLR4, TLR3, TLR7, TLR8, and TLR9 in the immunopathogenesis of common variable immunodeficiency—CVID (as PID)—and chronic lymphocytic leukemia—CLL (as SID)." (PMID 37626865, 2023).
congenital Zika syndrome (1 paper, 2023). "Another study also demonstrated that Smadcin‐6, a Smad6‐derived peptide, interacts with Peli1 to disrupt Peli1‐mediated TLR4 signalling, and that it also showed therapeutic effects in lethal inflammatory disease and congenital Zika syndrome." (PMID 37341064, 2023).
cryopyrin-associated periodic syndrome (1 paper, 2018). Cryopyrin associated periodic syndrome (CAPS) defines a group of autoinflammatory diseases, characterized by recurrent episodes of systemic inflammatory attacks in the absence of infection or autoimmune disease. "Remarkably, single TLR4 stimulation is sufficient to activate massive, GSDMD-mediated IL-1β secretion in monocytes from patients affected by Cryopyrin Associated Periodic Syndrome (CAPS), an autoinflammatory disease linked to NLRP3 mutations." (PMID 30352992, 2018).
cystic ovary (1 paper, 2023). "In the case of the TLR4 variant g.9422T>C (rs8193060), indications were obtained for the association with as many as four reproductive traits: incidence of cystic ovaries, early reproductive disorders, calving ease, and production longevity." (PMID 38254914, 2023). "In the case of the TLR4 variant g.9422T>C, indications were obtained for the association with four different reproductive traits: cystic ovary incidence, early reproductive disorders, calving ease, and production longevity." (PMID 38254914, 2023).
deafness (1 paper, 2015). An inherited or acquired condition characterized by the complete loss of the ability to hear from one or both ears. "Thus, TLR4 promotes pathology-induced bone destruction and deafness by enhancing inflammatory responses and osteoclastogenesis." (PMID 26639190, 2015).
diabetic encephalopathy (1 paper, 2024). A brain disease that is characterized by functional impairment of cognition, cerebral signal conduction, neurotransmission and synaptic plasticity, and underlying structural pathology associated with diabetes. "In the CNS, miR-218-5p inhibits neuroinflammation in diabetic encephalopathy via targeting TLR4." (PMID 38229084, 2024).
diverticular disease (1 paper, 2014). A complex disorder characterised by mucosal outpouchings (diverticulae) of the colonic wall which can become infected and inflamed leading to diverticulitis, perforation and bleeding. "Then, we hypothesized that a defect in TLR4 expression predisposes to diverticular disease by impairing antibacterial defense." (PMID 25133198, 2014).
Dry skin (1 paper, 2023). Skin characterized by the lack of natural or normal moisture. "TLR4 plays an important role in dry skin–induced persistent itch." (PMID 36520531, 2023).
ductal carcinoma in situ (1 paper, 2013). "We have previously demonstrated that tumor antigen-bearing dendritic cells generated using IFN-γ and the TLR-4 agonist LPS (referred to here as DC1 dendritic cells) promote a targeted immune response in patients with ductal carcinoma in situ." (PMID 24244265, 2013). "We have previously detailed our clinical results using a TLR-4-activated dendritic cell vaccine to engender an antigen-specific immune response and prevent recurrence of HER-2/neu-positive ductal carcinoma in situ." (PMID 24244265, 2013).
Dysmenorrhea (1 paper, 2017). Pain during menstruation that interferes with daily activities. "After statistical analysis confirmed that: The gene expression of TLRS (TLRS = TLR1 + TLR2 + TLR3 + TLR4 + TLR5 + TLR6 + TLR7 + TLR8 + TLR9) in severe and moderate dysmenorrhea group was significantly higher than that in minimal dysmenorrhea group in EU and EC (P < 0.05 or P < 0.01)." (PMID 28779087, 2017).
dystrophin deficiency (1 paper, 2023). "Our finding of increased TLR4 expression with both dystrophin deficiency as well as HFHSD groups support previous reports, and is suggestive of additive effects of DI-IR on dystrophin deficiency." (PMID 37811713, 2023).
egg allergy (1 paper, 2016). A food allergy that is an allergy or hypersensitivity to dietary substances from the yolk or whites of eggs, causing an overreaction of the immune system which may lead to severe physical symptoms. "This approach identified several novel processes not previously associated with egg allergy, including positive associations with TLR4-stimulated myeloid cells and activated NK cells, and negative associations with an induced Treg signature." (PMID 27788149, 2016).
embryonal carcinoma (1 paper, 2014). A non-seminomatous malignant germ cell tumor characterized by the presence of large germ cells with abundant cytoplasm resembling epithelial cells, geographic necrosis, high mitotic activity, and pseudoglandular and pseudopapillary structures formation. "Expression of TLR4 and MyD88 was assessed immunohistochemically in 198 paraffin-embedded ovarian tissues and in an embryonal carcinoma model of cancer stemness." (PMID 24977712, 2014).
endometrial adenocarcinoma (1 paper, 2008). "TLR3 and TLR4 mRNA expression varied significantly between control, hyperplasia and endometrial adenocarcinoma samples (Kruskal-Wallis test, P < 0.01)." (PMID 18775079, 2008). "TLR3 and TLR4 expression was investigated during the menstrual cycle and in postmenopausal endometrium considering peritoneal endometriosis, hyperplasia, and endometrial adenocarcinoma specimens (grade 1 to 3)." (PMID 18775079, 2008).
enterovirus infection (1 paper, 2019). "It is still unclear how TLR4 detects enterovirus infection; however, evidence points to a role of TLR4 in the induction of proinflammatory cytokines and clinical pathology during infection." (PMID 31117206, 2019). "Although TLR4 is thought to be key during bacterial infection since it mainly senses lipopolysaccharide (LPS), a protein found on gram negative bacteria, TLR4 plays an important role in secondary target tissues (tissues other than the route of entry) of enterovirus infection." (PMID 31117206, 2019).
eosinophilic esophagitis (1 paper, 2023). Eosinophilic esophagitis (EoE) is a chronic, allergic disease of the esophagus characterized clinically by symptoms of esophageal dysfunction (including vomiting, dysphagia, feeding disorders, food impaction and abdominal pain) which persist after treatment with proton pump inhibitors (PPIs). "The aim of this study was to assess the physical association of TLR4 with LPS in patients with active and inactive eosinophilic esophagitis." (PMID 38024851, 2023).
eosinophilic granulomatosis with polyangiitis (1 paper, 2024). Eosinophilic granulomatosis with polyangiitis (EGPA), previously known as Churg-Strauss syndrome, is a systemic vasculitis of small-to medium vessels, characterized by asthma, transient pulmonary infiltrates, and hypereosinophilia. "Similarly, a lower expression of TLR4 was observed in the mDCs of relapsed eosinophilic granulomatosis with polyangiitis (EGPA) patients relative to EGPA patients in remission or non-EGPA patients." (PMID 39238498, 2024).
epididymo-orchitis (1 paper, 2025). A disorder involving inflammation of the epididymis and testes. "TLR4 has been previously characterized as a receptor mediating S100A4 signaling; our study reveals a distinct pathological mechanism underlying UPEC-induced epididymo-orchitis." (PMID 41031892, 2025).
Epiretinal membrane (1 paper, 2024). An epiretinal membrane is a thin sheet of fibrous tissue on the surface of the retina along the inner limiting membrane. "The aim of this study was to confirm the expression of TLR2 and TLR4 in the fibrocellular membranes and vitreal fluids (soluble TLRs) of patients suffering of epiretinal membranes (ERMs) and assess their association with disease severity, complement fragments and inflammatory profiles." (PMID 39062973, 2024).
equine diseases (1 paper, 2019). "Because of the relative importance of endotoxin in a number of equine diseases, Toll-like receptor 4 (TLR4), which binds the lipid A component of LPS, has been the subject of much research and will be further discussed." (PMID 30931316, 2019).
esophageal carcinoma in situ (1 paper, 2024). "We confirmed these results in a mouse model of 4NQO-induced esophageal carcinoma in situ and further identified epithelial–mesenchymal transition (EMT) occurrence and TLR4/Myd88/NF-κB pathway activation in mouse esophageal tumors." (PMID 38834834, 2024).
esophageal disorder (1 paper, 2025). A non-neoplastic or neoplastic disorder that affects the esophagus. "Furthermore, advances in glycoengineering could enable the manipulation of LPS structures, offering new potential therapeutic strategies such as engineered probiotics or synthetic glycans to modulate TLR4 signaling and restore immune balance in these esophageal disorders." (PMID 41226900, 2025).
extrapulmonary tuberculosis (1 paper, 2023). A tuberculosis that occurs at body sites other than the lung. "TLR-2 and TLR-4 serum scores were higher in patients with extrapulmonary tuberculosis, in addition to serum TLR-2, TLR-4 was higher in those with BCG scars than in those without BCG, and statistical analysis results showed a significant difference." (PMID 38129893, 2023).
eye inflammation (1 paper, 2015). "In the last few years, experimental animal models have enabled us to better understand the leading role of macrophages in eye inflammation processes, counting macrophage polarization and the significant role of TLR4." (PMID 26078494, 2015).
Fanconi anemia (1 paper, 2021). Fanconi anemia (FA) is a hereditary DNA repair disorder characterized by progressive pancytopenia with bone marrow failure, variable congenital malformations and predisposition to develop hematological or solid tumors. "Among them, cysteine dioxygenase 1 (CDO1), toll-like receptor 4 (TLR4), and dual oxidase 1 (DUOX1) were downregulated in tumors and played a protective role, while Fanconi anemia complementation group D2 (FANCD2) and others were with high expression in tumors and were risk factors for prognosis." (PMID 34820377, 2021).
Fulminant hepatitis (1 paper, 2024). Acute hepatitis complicated by acute liver failure with hepatic encephalopathy occurring less than 8 weeks after the onset of jaundice. "In mice with fulminant hepatitis, TEC can protect the liver against inflammatory damage by downregulating TLR4, IL‐6, TNF‐α, iNOS, and COX‐2 expressions." (PMID 38722267, 2024).
gangrene (1 paper, 2025). Death of tissue, usually in considerable mass and generally associated with loss of vascular (nutritive) supply and followed by bacterial invasion and putrefaction. "Through a systematic analysis of 12 drugs and six key genes (IGF1, IL17A, ACE, FGF2, IL6 and TLR4), we have provided a new scientific perspective on gangrene prevention in diabetic patients." (PMID 40657379, 2025).
gastric cardia carcinoma (1 paper, 2018). A carcinoma that arises from epithelial cells of the cardia of stomach. "Similar to other studies, our study showed that normal gastric cardia cancer has a very low expression of TLR4." (PMID 29670922, 2018).
gastric MALT lymphoma (1 paper, 2014). "The TLR4 Asp299Gly genotype acts as a protective factor during the development of gastric MALT lymphoma in Caucasians." (PMID 24959291, 2014).